PDE11A (phosphodiesterase 11A)
Diseases named in the same sentence as PDE11A in open-access papers (continued):
Sharing a sentence is not in itself a finding about the gene and the disease.
testicular cancer (2 papers, 2021 to 2022). A primary or metastatic malignant neoplasm that affects the testis. "The role of PDE11A polymorphisms has been explored in various diseases but recent studies highlighted their contribution also in testicular cancer." (PMID 33661511, 2021). "Our findings highlight the key role of PDE11A in testis and suggest the presence of an underlying complex and fine molecular mechanism which controls testis-specific gene expression and susceptibility to testicular cancer." (PMID 33661511, 2021). "The aim of this study was to investigate testicular function and PDE11A sequence in testicular cancer cases." (PMID 33661511, 2021). "Studies of adrenal, prostate and testicular cancer have suggested that PDE11A variants may represent susceptibility modifiers rather than direct and sufficient causes of these neoplasms." (PMID 33661511, 2021). "However, PDE11A sequencing revealed ten new polymorphisms not yet associated with testicular cancer before: four for the Fragment1 (C207T, G223A, A288G, T366C) and six for the Fragment2 (C102A, G172A, C189T, T245C, C255A, G371C)." (PMID 33661511, 2021).
acromegaly (1 paper, 2019). Acromegaly is an acquired disorder related to excessive production of growth hormone (GH) and characterized by progressive somatic disfigurement (mainly involving the face and extremities) and systemic manifestations. "The presence and role of PDE11A expression and variants were studied in somatotroph adenomas." (PMID 30941100, 2019).
Alcoholism (1 paper, 2014). "Furthermore, the Collaborative Study on the Genetics of Alcoholism (COGA) identified a candidate single nucleotide polymorphism near PDE11A based on differing allele frequencies between alcohol-dependent and control individuals." (PMID 24904269, 2014).
atrial fibrillation (1 paper, 2025). A disorder characterized by an electrocardiographic finding of a supraventricular arrhythmia characterized by the replacement of consistent P waves by rapid oscillations or fibrillatory waves that vary in size, shape and timing and are accompanied by an irregular ventricular response. "A recent study validated a set of five differentially expressed and co-upregulated genes (DEGs) (DGAT1, AMOT, PDE11A, TYMS, and TMEM98) that were elevated in patients with atrial fibrillation, liver disease, and atrial fibrillation associated with liver disease compared to healthy controls." (PMID 40141794, 2025).
breast carcinoma (1 paper, 2023). "In our experiments, we observed three different expression patterns for PDE11A in three distinct breast cancer cell lines." (PMID 37607966, 2023).
cardiomyopathy (1 paper, 2022). A disease of the heart muscle or myocardium proper. "These include a high positive selection on KAI14, KIF6 (both indicated in cardiomyopathy), and PDE11A (vasoregulation), as well as pathway enrichments for the renin-angiotensin system and the endothelin-1 pathway, identified in both WedAR and dN/dS analyses." (PMID 35177770, 2022). "The three genes under the greatest positive selection in the dN/dS analysis are implicated in either cardiomyopathy (RAI14, KIF6) or vasoregulation (PDE11A)." (PMID 35177770, 2022).
COVID-19 (1 paper, 2022). A disease caused by infection with severe acute respiratory syndrome coronavirus 2. "PDE11A is known to be involved in inflammatory response and is abundantly expressed in the severe COVID-19 patients." (PMID 36532041, 2022).
hyperopia (1 paper, 2014). A refractive error in which rays of light entering the eye parallel to the optic axis are brought to a focus behind the retina, as a result of the eyeball being too short from front to back. "However, the signal in our hyperopia analysis stretches across 3 genes: PDE11A; tetratricopeptide repeat domain 30A (TTC30A) protein; and alkylglycerone phosphate synthase (AGPS, MIM:603051)." (PMID 25233373, 2014).
liver cancer (1 paper, 2023). An epithelial or non-epithelial malignant neoplasm that arises from the liver. "Three novel gene–cancer associations were found in this study, namely, PDE11A and PALB2 with lung cancer and SLX4 with liver cancer." (PMID 37610374, 2023).
lung carcinoma (1 paper, 2023). "In this study, the recurrent PDE11A c.20_21del truncating variants were found in two lung cancer patients, suggesting its correlation with lung cancer and tumor suppression." (PMID 37610374, 2023).
myxoma (1 paper, 2025). A benign soft tissue neoplasm characterized by the presence of spindle and stellate cells, lobulated growth pattern, and myxoid stroma formation. "Studies have implicated recurrent somatic mutations in PRKAR1A, as well as alterations in cAMP pathway genes such as PRKACA and PDE11A, suggesting a shared pathogenic mechanism between sporadic and familial myxomas." (PMID 40264618, 2025).
neoplastic syndrome (1 paper, 2018). A broad classification for disorders in which the development of neoplasms typically occur in association with a characteristic set of signs or symptoms. "Furthermore, analysis of genes associated with risk of other inherited neoplastic syndromes different to HBOC identified heterozygous pathogenic variants for MSR1 (4%, 2/52), LIG4 (4%, 2/52) and PDE11A (6%, 3/52) in the affected women in both groups." (PMID 30262796, 2018).
pituitary adenoma (1 paper, 2019). "PDE1, PDE2, PDE4, and PDE11A are highly expressed in the pituitary, and overexpression of some PDE4 isoforms have been demonstrated in different pituitary adenoma subtypes." (PMID 30941100, 2019).
pituitary tumor (1 paper, 2023). A benign or malignant neoplasm affecting the pituitary gland. "have postulated the role of other genes in the development of pituitary tumors in AIPvar carriers, namely PDE11A (associated with adrenal tumorigenesis) and ALG (coding a protein essential for glycoprotein folding and stability)." (PMID 36843582, 2023).
preeclampsia (1 paper, 2024). Preeclampsia is a hypertensive disorder of pregnancy that is characterized by new-onset hypertension with proteinuria presenting after 20 weeks of gestation, and depending on mild or severe forms may initially present with severe headache, visual disturbances, and hyperreflexia. "Coincidentally, mutations in the PDE11A gene have also been found to be associated with preeclampsia, premature birth and stillbirths." (PMID 38473152, 2024).
tumor (11 papers, 2016 to 2025). "Western blot analyses of tumor tissues from affected patients with PDE11A mutations revealed a marked reduction in PDE11A4 protein levels compared to normal adrenal tissue." (PMID 41511347, 2025). "Third, the allelic losses of the wild-type allele in ACC with missense mutations supports PDE11A role as a tumor suppressor gene." (PMID 27625633, 2016). "Further study of these questions should provide additional support for the role of PDE11A as a tumor suppressor and our knowledge of germ cell proliferation and development." (PMID 36313756, 2022). "PDE11A appears to act as a tumor suppressor gene in NSGCT, as NSGCT patients with PDE11A mutations are more likely to have a family history of NSGCT and/or to present at a younger age, and/or to present with bilateral tumors." (PMID 36313756, 2022). "These tumors showed 2q31–2q35 loss of heterozygosity (LOH) and elevated cAMP levels, supporting PDE11A’s role in tumor formation." (PMID 27625633, 2016). "This suggests that PDE11A has a tumor‐suppressing function in the lungs." (PMID 37610374, 2023). "Additionally, the authors observed a four-fold increase in phosphorylated CREB (pCREB) to total CREB ratios in tumor tissues, likely reflecting enhanced cAMP/PKA signaling due to reduced PDE11A-mediated degradation of cyclic nucleotides." (PMID 41511347, 2025).
cancer (5 papers, 2019 to 2023). A tumor composed of atypical neoplastic, often pleomorphic cells that invade other tissues. "Activators of PDE8 and PDE11 would have potential value in the treatment of tumors with hemizygous loss or inactivation of PDE8B of PDE11A, respectively, and potentially in other cAMP-pathway cancers characterized by elevated levels of cAMP." (PMID 36313756, 2022). "Functionally, these differences in context help to explain the clinical and biological differences in cancers that contain the same driver mutation (e.g., the diverse cancers with mutations in PDE11A or with those with mutations in CREB/ATF/CREM)." (PMID 36313756, 2022). "It is likely that further studies of the biochemical effects of the various mutations, especially on proteins, such as PDE11A, that are mutated in a wide range of different cAMP-pathway cancers, will provide additional insights into the basic mechanisms of regulation of these pathway components." (PMID 36313756, 2022). "However, for other drivers (e.g., PDE11A), there is no obvious difference in the mutational pattern of the driver in various clinically and biologically diverse cancers." (PMID 36313756, 2022).
PDE11A also shares sentences with these, for which no sentence is quoted: adrenal cortical tumors (2 papers); major depression (2); primary pigmented nodular adrenocortical disease (2); prostate carcinoma (2); Testicular Large Cell Calcifying Sertoli Cell Tumor (2); bipolar disorder (1); central obesity (1); colon (1); cryptorchidism (1); familial tumor syndromes (1); hereditary leiomyomatosis (1); Hypertension (1); Insulin resistance (1); liver disease (1); renal cell carcinoma (1); Stillbirth (1).